RAG2 (recombination activating 2)
Diseases named in the same sentence as RAG2 in open-access papers (continued):
Sharing a sentence is not in itself a finding about the gene and the disease.
tumor (continued). "Immunodeficient recombination activating gene-2 (rag2)−/− mice, lacking both T and B cells, were inoculated with TC1 tumor cells and treated with adoptive cell transfer (ACT) of CD8+ T cells from either wt or cblb-deficient donor mice." (PMID 25815272, 2015). "However, in RAG2−/− mice, d106S-IL12 led to only a partial slowing of tumor growth and no equilibrium, suggesting that adaptive immunity was necessary to stably control tumors." (PMID 36881506, 2023). "Another interesting finding is that depletion of RAG1 or RAG2 elicits T-ALL cell growth inhibition (data not shown), suggesting that these recombination activation genes may have other tumor-promoting roles in cells already transformed." (PMID 34322489, 2021).
infection (88 papers, 2005 to 2025). The state of being infected such as from the introduction of a foreign agent such as serum, vaccine, antigenic substance or organism. "Our results detected a differential increased expression of the troph versus ascus marker in immunocompromised Rag2–/– mice at increased risk for active infection versus WT mice." (PMID 40029713, 2025). "Rag2-/-Tyk2-/- and Rag2-/-Tyk2K923E mice showed a comparable fungal burden in the skin as Rag2-/- control animals on day 4 p.i, as well as similar infection-associated changes in the white blood cell composition." (PMID 39622833, 2024). "ILC2s are essential mediators of the immune response to L. sigmodontis and depletion of ILC2s in T and B cell-deficient Rag2-/- mice enhanced the susceptibility to the infection as was shown by an increase in microfilariae numbers in the peripheral blood." (PMID 35757689, 2022). "Infected Rag2−/− mice showed no significant loss of body weight, but the average body weight of the Rag2−/− mice was lower than that of both challenged and unchallenged wild-type mice from the 6th day post infection." (PMID 36016362, 2022). "A similar trend was observed for the RAG2 deficiency with only 20% (1/5) of the mice retaining adult B. malayi parasites by 12 week p.i. despite 86% positive infection (6/7) at 1 week p.i.." (PMID 36238293, 2022). "Strikingly, mice lacking T-bet were more susceptible to T. gondii compared to Rag2-/- animals and were unable to survive past day 10 of the acute stage of infection." (PMID 33465134, 2021). "As ΔespO cause a significantly reduced cell proliferation, a marker of tissue damage repair, we determined the outcome of infection of the highly susceptible Rag2-/- il2rg-/- mice (n = 5), which lack NK, ILCs, T and B cells." (PMID 30365535, 2018). "The intensity and duration of bioluminescence signal were enhanced in Rag2-/- rats compared to that in wild type rats, confirming that immunodeficient animals are more susceptible to rTV-Fluc infection." (PMID 26235050, 2015). "We also demonstrated that the immunodeficient Rag2-/- rats with deficiency of T/B cells were more susceptible to rTV-Fluc infection, with extended infection duration, less weight gain, and pathological changes in the spleen, kidney and lung." (PMID 26235050, 2015). "Rag2-/- mice, however, showed similar weight loss kinetics in the early stages after infection but weight loss continued post infection and culminated in death." (PMID 20667098, 2010). "Here, we have followed the survival, weight loss, viral load and lung pathology in Rag2-/- knock-out mice after infection with influenza A virus (H1N1)." (PMID 20667098, 2010). "Infection caused only two uniquely upregulated genes, Il10 (IL-10) and Rag2." (PMID 37929965, 2023). "In Rag2 knockout mice, the depletion of NKp46+ cells increased susceptibility to infection." (PMID 37325618, 2023). "Finally, we demonstrate that in RAG2 deficient mice, drug clearance of a primary adult B. malayi infection followed by challenge infection leads to resistance against early larval B. malayi establishment." (PMID 36238293, 2022). "Moreover, the repeatability between different rats was poor, and only 33% of Rag2-deficient rats was positive for infections and bioluminescent signals." (PMID 26235050, 2015). "RAG2−/− common–chain−/− mice were 100 fold more susceptible to infection than RAG2−/− mice." (PMID 25197644, 2014). "Concurrently, both WT and RAG2-/- hypothyroid mice developed higher disease scores from the infection’s onset, during which the innate immune system governs the immune response." (PMID 41263555, 2025). "The dams were sacrificed on 3–9 days post-infection (dpi) to prevent a reduced health status normally occurring in Rag2-/-Il2rg-/- and Ifnar1-/- pregnant mice upon infection with high MCMV doses." (PMID 41288331, 2025).
infection (continued). "As expected, an overall higher parasitaemia was detected in Rag2-/- mice when compared to WT mice, due to the known role of the T and B cells to control infection." (PMID 39654402, 2024). "Three days after infection, the transduced HSPCs were sorted and transplanted into irradiated Rag2-/-γc-/- mice." (PMID 39043964, 2024). "Following challenge with 105 PFU of WRvFire, the C57Bl/6 and Rag2 KO mice that received the control serum rapidly lost weight and succumbed to the infection." (PMID 39719481, 2024). "This was evident as Rag2−/− showed heightened vulnerability to infection and inhibited viral clearance." (PMID 38675952, 2024). "hCsf2/Il3 DKI mice exhibited ~103-fold increased lung CFUs 24 h after SPn14 infection alone, as compared with Rag2-/-Il2rg-/- controls." (PMID 37771584, 2023). "The authors further showed that the long-term activation of NKp46+ cells plays a protective role during secondary infection in Rag2 knockout mice, proving that memory is intrinsic to the innate compartment." (PMID 37325618, 2023). "In contrast, we would expect that the same treatment in a 1/148 infection would result in prolonged survival, mimicking the effect we observed in RAG2 KO mice." (PMID 35787830, 2022). "Percentage of leukocytes found in the brain vasculature at day 6 post-infection in RAG2 KO mice relative to WT control." (PMID 35787830, 2022). "The present findings suggest differences in macrophage activation contribute to the inflammatory process and lead to distinct lesion pathology during 5-ASKH and FV9 infection in Rag2−/− mice." (PMID 36190414, 2022). "(F) ASAT plasma levels of LPS or NaCl pretreated Rag2-/- mice at 18 hr p.i. with E. coli, which have been reconstituted with bone marrow derived B cells 3 weeks before infection." (PMID 36178806, 2022). "NKp46+ NK cell expansion was intact and similar to WT mice after one-week infection in RAG2-/- mice." (PMID 36238293, 2022). "In contrast, C57BL/6 Rag2 knockout mice, which lack T and B lymphocytes, show distinct pathologies during infection with these strains." (PMID 36190414, 2022). "Infection of Rag2-/- mice resulted in a significantly higher worm burden compared to wild-type C57BL/6 mice 30dpi with 100% of the worms being adult in Rag2-/- mice and 30% in C57BL/6 mice." (PMID 35757689, 2022). "Top: Neuropathology score at day 6 post-infection of RAG2 KO and WT mice infected with T. congolense 1/148 (N=4–5)." (PMID 35787830, 2022). "(D) Schematic showing infection of Rag2-/-Ggta1+/+ mice with a cecal inoculum from either Ggta1+/+ or Rag2-/-Ggta1+/+ mice." (PMID 34009123, 2021). "It was demonstrated that intravenously administered Leishmania parasites trafficked to the skin of B6.Rag2-/- mice, establishing macro- and microscopic pockets of skin resident infection." (PMID 34613967, 2021). "(F) CFU of Ae and An bacteria in Rag2-/-Ggta1-/- mice (n = 4 per group), 24 hr after infection as in (E); one experiment." (PMID 34009123, 2021). "To further explore if ILC1s were sufficient and necessary for maintaining DCs during infection, we next tested the effects of selective depletion of Thy1+ cells in WT and Rag2-/- mice." (PMID 33465134, 2021). "(E) Survival of Rag2-/-Ggta1+/+ (n = 5) mice after infection with a cecal inoculum from Ggta1+/+ mice, and Rag2-/- Ggta1+/+ (n = 5) mice after infection with a cecal inoculum from Rag2-/-Ggta1+/+ mice; one experiment." (PMID 34009123, 2021). "Organ titers were also comparable for all three viruses in spleen, liver, kidney and brain of infected Rag2-/- and WT mice at 17 days post infection." (PMID 34194424, 2021). "(C) Colony-forming units (CFU) of aerobic (Ae) and anaerobic (An) bacteria in Rag2-/-Ggta1-/- mice (n = 5 per group), 24 hr after infection as in (B); two experiments." (PMID 34009123, 2021). "(A) Schematic showing infection of Rag2-/-Ggta1-/- mice with a cecal inoculum from either Ggta1-/- or Rag2-/-Ggta1-/- mice." (PMID 34009123, 2021).
infection (continued). "This serial passaging in Rag2-/- mice was performed nine times during which we observed a decrease in time of onset of severe disease (> day 28 post-infection (PI) for passage 1 to <day 7 PI passage 9)." (PMID 33416494, 2021). "(B) Survival of Rag2-/-Ggta1-/- (n = 9) mice after infection with a cecal inoculum from Ggta1-/- mice, and from Rag2-/-Ggta1-/- (n = 9) mice after infection with a cecal inoculum from Rag2-/-Ggta1-/- mice; two experiments." (PMID 34009123, 2021). "After experimental infection of RAG2-/-IL-2γc-/—mice, the average L. loa juvenile adult worm recovery rate was 10.5% at 62 dpi." (PMID 32804951, 2020). "(D) Quantification of Ly6Chi and Ly6Clo dermal Mφ in naïve and primed Rag2–/–γc–/– mice 5 days after (re-)infection." (PMID 32639232, 2020). "The AFP secretion in the mouse serum after paOAd infection was significantly decreased by blue light irradiation in the Rag2-Il2rg double-knockout mice transplanted with CD133-positive HepG2 cells, while that did not change by Sorafenib treatment." (PMID 32703933, 2020). "To characterize the inflammation induced by either L. major Friedlin or 5ASKH infections, we isolated immune cells from Rag2 KO-infected footpads at 4 weeks post-infection and analyzed these cells by flow cytometry." (PMID 31738761, 2019). "Immune cells were isolated from the footpads of Rag2 KO mice 4 weeks after infection with L. major Friedlin or 5ASKH and were cultured for 72 h with or without PMA-ionomycin stimulation." (PMID 31738761, 2019). "Conversely, all BALB/c RAG2−/− mice had cleared infection at 5 months (0/10 mice infected, p < 0.0001 when comparing BALB/c RAG2−/−γc−/− to BALB/c RAG2−/− mice, Mann–Whitney test)." (PMID 30926803, 2019). "In summary, we found that the number of T cells per NIF increased over time in wild-type mice and that adoptive transfer of 107 naïve T cells into Rag2-/- mice was necessary to accumulate enough T cells in NIFs to control the infection." (PMID 30153311, 2018). "pylori colonies were isolated from the stomachs of RAG2−/− and WT mice (N = 4–7) at 2 and 8 weeks post infection (PI)." (PMID 28418004, 2017). "One day post transfer, RAG2-/- mice were infected with L. donovani and the outcome of infection assessed at day 28 p.i., as a measure of functional antigen-specific T cell responses." (PMID 27658046, 2016). "One RAG2/IL2RG deficient Gn pig was euthanized at 3 days of age due to general weakness rather than illness caused by pathogens; and one was used as a mock infection control." (PMID 27118081, 2016). "The cellular composition of the spleens in reconstituted RAG2-/-γc-/- mice reflected the origin of the transferred cells, but also mirrored the situation found in WT or CatB-/- mice post infection, with more CD4 and less CD25+CD4+ cells." (PMID 27182703, 2016). "In Rag2-/- rats, IV inoculation produced a more intense luminescent signal spreading to other organs in limb and head region by day 1 post infection." (PMID 26235050, 2015). "By contrast, the bacterial burden after challenge infection in RAG2-/- mice was similar to that after primary infection." (PMID 26182347, 2015). "The body weight gain in IV infected Rag2-/- rats was significantly less than in other groups after infection." (PMID 26235050, 2015). "In contrast, in the rTV-Fluc/immunodeficient Rag2-/- rat model, luminescent signal was readily visible at 6 hours post infection and had a similar distribution pattern as that in rTV-Fluc/immunocompetent rats." (PMID 26235050, 2015). "The infection time course was significantly increased in Rag2-/- rats than that in SD rats after IV inoculation (>35 days IV vs <6 days IV, p < 0.05)." (PMID 26235050, 2015). "Similar to infection with WT J166, colonization density of mOut2 was greater in RAG2−/− mice than in C57BL/6 mice." (PMID 23468628, 2013).
infection (continued). "Additional evidence that mTXNPx is not implicated in Leishmania protection against host-derived oxidants was obtained in an in vivo infection experiment using mutant mice with impaired pro-oxidant capacity, namely B6.p47phox−/− and B6.RAG2−/− IFN-γ−/− mice." (PMID 22046130, 2011). "Viral load was studied in wild type and Rag2-/- mice as described after infection with 2 × 103 FFU of influenza A virus PR8 (H1N1)." (PMID 20667098, 2010). "In contrast, HSV-2 0ΔRING infection was fatal in only 2 of 10 rag2−/− mice over a 100-day observation period." (PMID 20808928, 2010). "All infected male Rag2-/- mice died between day 12 and day 18 after infection whereas wild type mice survived." (PMID 20667098, 2010). "HSV-2 0ΔNLS and 0ΔRING produced infections that slowly progressed towards lethal disease in rag2−/− mice." (PMID 20808928, 2010). "Wild type and Rag2-/- mice differed markedly in the severity and type of pulmonary lesions at later time points after infection." (PMID 20667098, 2010). "As is the case for wild-type mice infected with CVS-F3, both JHD−/− and RAG-2−/− mice lose weight as the infection progresses." (PMID 19806203, 2009). "Once the HIV-1 humanized mouse model was established in Rag2-/-γc-/- animals, multiple studies have improved upon the model through increased robustness of infection and the generation of infectable human cells." (PMID 19674458, 2009). "This study proved that the Rag2-/-γc-/- humanized mouse model can support an active infection in vivo and provide characteristic symptoms of viremia as seen in humans." (PMID 19674458, 2009). "Specifically, it was found that the Treg cells and their interaction with the FoxP3 transcription factor (CD4+FoxP3+ cells) allow for the preferential infection by HIV-1 in the Rag2-/-γc-/- animals." (PMID 19674458, 2009). "RAG-2 deficient hosts were reconstituted with OT-I WT TamCre CD45.1 or OT-I Mrtfa−/−Mrtfbfl/fl TamCre CD45.2 bone marrow, treated with tamoxifen to inactivate Mrtfb, and subsequently co-transferred with OT-I WT cells to new hosts for infection analysis." (PMID 39261466, 2024). "Furthermore, BALB/c Rag2-/-Il2rg-/- mice were competent in acute bacterial clearance before and after PR8 or X31 infection, despite their deficiency in adaptive antiviral immunity." (PMID 37771584, 2023). "We also found a significant increase of Ifng expression in the gut of Rag2-/- 24h after the infection with C. parvum, suggesting that the cytokine may also be involved in the early immune response against the parasite." (PMID 37744354, 2023). "To identify immune mechanisms activated during the very early phase of C. parvum infection, we first analyzed the expression of genes related to key effector functions of innate immune cells such as interferons and granzymes in the small intestine of adult Rag2-/- mice 24h post-infection (PI)." (PMID 37744354, 2023). "So, we assessed several infection parameters in RAG2 KO mice and compared them to WT mice." (PMID 35787830, 2022). "T. congolense 1/148 sequestration and infection progression in RAG2 KO mice." (PMID 35787830, 2022). "A humanized monoclonal antibody showed strong antiviral activity in this animal model, implying that Rag2−/− mice that support long-term stable infection are a useful tool for studying the transmission and pathogenesis of human RSV, as well as evaluating therapeutics." (PMID 36016362, 2022). "RAG2−/− mice infected with Leishmania major demonstrated susceptibility to infection due to the absence of CD4+ T lymphocytes." (PMID 32867857, 2020). "Due to the high reproducible parasitological success of mature L. loa in compound deficient mice at 5 months post infection, we surgically implanted recovered female and male worms (n = 5 per sex) subcutaneously into NOD.SCIDγc−/− or BALB/c RAG2−/− recipient mice." (PMID 30926803, 2019).